SIRT1 (sirtuin 1)
Diseases named in the same sentence as SIRT1 in open-access papers (continued):
Sharing a sentence is not in itself a finding about the gene and the disease.
Hyperglycemia (continued). "Because SIRT1 requires NAD for its enzymatic activity, a decline in NAD biosynthesis on high glucose or hyperglycemia may result in a significant reduction of SIRT1 levels and subsequent loss of the glucose- or insulin-responsive phenotypes." (PMID 23734259, 2013). "Moreover, EX-527 notably detracted from melatonin’s protective stance against sepsis-induced liver damage, hyperglycemia, and STAT3 deactivation, proffering prospects for melatonin’s approach in treating sepsis-induced liver damage through SIRT1-mediated STAT3 pathways." (PMID 38690282, 2024). "Final SIRT1 concentrations in the BC of the BBB model in all glycemic backgrounds were comparable at the limit of detection and equaled 13 pg/μL for hypoglycemia (6% of its initial value) and 43 pg/μL for normo- and hyperglycemia (21% of their respective initial values)." (PMID 37511397, 2023). "In addition, the depletion or inhibition of KMT6A attenuated the increase of ROS in hyperglycemia-treated human renal tubular epithelial cells, while the KMT6A knockdown attenuated the reduced expression of silent information regulator 1 (SIRT1) by hyperglycemia treatment." (PMID 36983082, 2023). "One concern with using an RNAi model to reduce Sirt1 expression is that the modifiers identified might be specific RNAi efficacy, rather than hyperglycemia." (PMID 35435227, 2022). "An earlier study, however, indicated that SIRT1 regulates pancreatic islet formation and differentiation through deacetylating FOXA2, and that pancreatic disruption of SIRT1 resulted in a progressive hyperglycemia together with glucose intolerance and a lack of insulin." (PMID 33806509, 2021). "Conversely, we observed here that hyperglycemia did not significantly affect kidney SIRT1 activity." (PMID 28079150, 2017). "However phosphorylation of ACC, a well described target of AMPK, was not changed by overexpression of SIRT1 in either the basal state or in response to hyperglycaemia, suggesting unaltered AMPK signaling in this model." (PMID 25798922, 2015). "Similarly, mice with global overexpression of SIRT1 do not show signs of hyperglycemia and are protected against glucose intolerance when fed high caloric diets." (PMID 24567900, 2014). "Hence, the effect of lowered SIRT1 expression, induced by either hyperglycemia or estradiol, on the cell remains unclear because no studies have been performed on basic parameters, such as cell viability and their response to standard stimulating factors." (PMID 37762053, 2023). "Moreover, hyperglycaemia reduced the expression of Bcl-2, and butein promoted Bcl-2 expression in hyperglycaemic NP cells; however, when Sirt1 was inhibited by Ex527, butein could no longer upregulate Bcl-2 expression in hyperglycaemic NP cells." (PMID 31583043, 2019). "From the obtained results, we concluded that the cytoplasmic SIRT1 expression was closely related to hyperglycemia‐induced neurodegeneration and AD pathogenesis with Aß accumulation and Tau phosphorylation, and the 2D Transwell system could not fully represent the in vivo hyperglycemia‐induced AD." (PMID 36073820, 2022). "Since SIRT1 levels in the PPS+PYR+EN group exceeded those in the non-treated litter-mate controls (non-DB), suggests that reduced SIRT1 levels may be an important part of the sclerosis phenotype and that intact SIRT1 levels may provide protect against hyperglycemia-induced GS." (PMID 30252878, 2018).
Sepsis (226 papers, 2013 to 2026). Sepsis is defined as life-threatening organ dysfunction caused by a dysregulated host response to infection. "UDCA modulates cellular signaling by decreasing pro-inflammatory pathways and activating anti-inflammatory pathways associated with SIRT1/Nrf2/HO-1 signaling, emphasizing its key role in myocardial protection during sepsis." (PMID 41898702, 2026). "In contrast, SIRT1 deficiency or reduced activity is strongly involved in the pathogenesis of various diseases, including sepsis and SAKI." (PMID 40698661, 2025). "Loss of SIRT1 facilitates Akt acetylation and thus promotes inflammatory cytokine production in mouse macrophages, potentially worsening the progression of sepsis in mice." (PMID 41416347, 2025). "Specifically, activation of SIRT1 leads to the deacetylation of Beclin1, which in turn promotes autophagy and mitigates kidney injury associated with sepsis." (PMID 39544947, 2024). "The consequences of sepsis-associated cell death are serious and treatments are urgently sought; estradiol and SIRT1 are investigated in this respect." (PMID 37762053, 2023). "Oleamide is an effective inhibitor of Cx43 channels, inhibiting ROS transfer and inactivating the JNK1/Sirt1/FoxO3a signaling pathway, thereby preventing damage caused by sepsis." (PMID 36579569, 2022). "To further investigate the underlying specifically regulation of SIRT1 on sepsis‐induced AKI, we sought to explore molecules that mediate this progress." (PMID 35137552, 2022). "The underlying mechanism of salvianolic acid B mitigating sepsis-induced liver injury is associated with the activation of the SIRT1/PGC-1α pathway." (PMID 35845569, 2022). "The activation of SIRT1 can alleviate normal cell apoptosis and reduce the degree of oxidation and inflammation, so as to reduce the systemic organ damage caused by sepsis." (PMID 34616305, 2021). "There is evidence that increased expression of SIRT1 can reduce multiple organ damage, including lung, kidney, and liver, caused by sepsis." (PMID 33557833, 2021). "Melatonin reportedly alleviates sepsis-induced multiple-organ injury, with the underlying mechanism mainly relying on SIRT1 activation." (PMID 33790896, 2021). "In the SIRT family, the role of SIRT1 in sepsis was reported in the most diverse manner, wherein the SIRT1 activation inhibits the inflammatory response caused by sepsis." (PMID 34445236, 2021). "The activation of SIRT1 inhibits apoptosis, oxidation, and inflammatory ions, thereby reducing the multiple organ damage caused by sepsis, including of the lung, kidney, and liver." (PMID 34721636, 2021). "The level of autophagy-associated proteins, phosphorylated (p)-AMPK/AMPK, and SIRT1 in the liver of CLP-induced sepsis mice peaked at 12 h post-CLP and decreased significantly at 24 h." (PMID 33981237, 2021). "SIRT1, a highly conserved mammalian NAD+-dependent histone deacetylase, is associated with the regulation of immune function, and SIRT1 knockout mice are highly susceptible to sepsis." (PMID 34055659, 2021). "The current study suggested that TUG1 was downregulated in sepsis and that its upregulation contributes to improved protection against the sepsis-caused inflammatory damage by impairing miR-9-5p-targeted inhibition of SIRT1." (PMID 34743197, 2021).
Sepsis (continued). "This study also highlights the proinflammatory mechanism associated with miR-9-5p-mediated inhibition of SIRT1, which contributes to a more comprehensive understanding of the pathogenesis of sepsis." (PMID 34743197, 2021). "Although the mechanisms of SIRT1 underlying sepsis have been increasingly recognized, its clinical implication in sepsis patients remains to be elucidated." (PMID 33263643, 2020). "Resveratrol treatment has also been shown to upregulate the expression of Sirt1, and IL-1β has been shown to be a proximal mediator of the inflammatory events associated with infection, sepsis, and ischemia." (PMID 30691208, 2019). "SIRT1 exerts protective properties during the development of sepsis, and some of the underlying mechanisms have already been identified." (PMID 30186119, 2018). "In the early stages of sepsis (1 h after CLP), SIRT1 expression is suppressed and cytokine levels are reduced; therefore, sepsis-associated coagulation disorders are reduced, and the incidence of marrow atrophy is also reduced." (PMID 30533222, 2018). "Based on these findings and on our previous studies, we investigated the contribution of Notch in sepsis and the association of SIRT1 with Notch signaling." (PMID 29867921, 2018). "We have found that SIRT1 deficient ob/ob mice show exaggerated microvascular inflammation during sepsis, which markedly increases mortality in comparison with lean mice." (PMID 26904696, 2016). "They found that SIRT1-mediated HMGB1 deacetylation inhibits sepsis-associated AKI." (PMID 41154674, 2025). "Moreover, irisin has been shown to suppress ferroptosis (a type of cell death elicited by iron-dependent lipid peroxidation) and protect from sepsis-associated acute kidney injury through activation of the sirtuin 1/Nrf2 (SIRT1/Nrf2) signaling pathway." (PMID 38540711, 2024). "Furthermore, silencing miRNA‐195 by gene KO can increase the expression of certain proteins—BCL‐2, Sirt1 and Pim‐1—and significantly reduce the potential trans‐organ damage associated with sepsis." (PMID 38014923, 2024). "Prior research has also shown that SIRT1 can alleviate sepsis-associated AKI (SA-AKI)." (PMID 38074159, 2023). "SIRT1 has been verified to be related with apoptosis and inflammation in cardiomyocytes and is also a key target for intervention therapy of alleviating myocardial injury caused by sepsis." (PMID 35223094, 2022). "Sepsis-induced serum transaminase activity and pro-inflammatory chemokine levels were decreased by resveratrol pretreatment, which also improved the liver histological parameters associated with the upregulation of SIRT-1." (PMID 35222035, 2022). "Furthermore, Kaplan-Meier analyses exhibited that SIRT1 high was associated with lower accumulating mortality in sepsis patients." (PMID 33263643, 2020). "Considering our findings that SIRT1 was negatively associated with inflammation and disease severity in sepsis patients, it was speculated that SIRT1 might be related to improved prognosis as well." (PMID 33263643, 2020). "This study indicated that SIRT1, in a later adaptive state of sepsis associated with modified bioenergetics, might contribute to immunosuppression." (PMID 30533222, 2018). "SIRT1/3 activation could therefore be a promising therapeutic strategy to treat sepsis-associated AKI." (PMID 28003866, 2016). "Given the reduced Sirt1 expression during aging, our results may provide an insight on why the elderly are more susceptible to sepsis-associated kidney injury." (PMID 24896770, 2014). "Additionally, irisin also could protect against sepsis-associated acute kidney injury through anti-ferroptosis via activating the SIRT1/Nrf2 axis." (PMID 38555440, 2024).
Sepsis (continued). "Therefore, it remains to be elucidated whether DEX confers protection against sepsis-associated AKI by activating the SIRT1/PGC-1α pathway and regulating mitochondrial function." (PMID 39455916, 2024). "Notably, SIRT1-mediated HMGB1 deacetylation mitigates acute kidney injury associated with sepsis." (PMID 38034869, 2023). "Considerable research has been performed to study SIRT1, a member of the sirtuin family that is a regulator of a variety of cellular and body processes, namely, metabolism, immune response, and aging, and studies have shown that sepsis is also closely associated with SIRT1." (PMID 34616305, 2021). "Quercetin alleviates sepsis-induced acute lung injury by activating the sirtuin 1 (SIRT1)/AMPK pathway to suppress oxidative stress (OS)-mediated ERS." (PMID 41614930, 2026). "In contrast, studies have reported that pterostilbene can ameliorate liver injury in sepsis model mice and reduce cardiotoxicity in doxorubicin-treated mice by upregulating Sirt1 gene expression." (PMID 40711451, 2025). "In summary, our study provides new insights into the role of Sirt1 in regulating the immune response during bacterial pneumonia and sepsis." (PMID 41096578, 2025). "In a mouse model of sepsis-induced liver failure, the upregulation of SIRT1 indicates a potential role in safeguarding hepatocytes from ferroptosis, lessening liver damage, and enhancing the clinical prognosis for liver failure." (PMID 40109363, 2025). "In sepsis, SIRT1 inhibits excessive inflammatory responses by deacetylating key proteins in the NF-κB and MAPK pathways." (PMID 41252417, 2025). "In contrast, the upregulation of SIRT1 in macrophages further contributes to the inhibition of proinflammatory cytokines via Akt activation in sepsis." (PMID 41416347, 2025). "Collectively, the data suggest that prolonged activation of the S1P1/SIRT1 signaling pathway protects against sepsis by inhibiting hyperinflammation and vascular hyperpermeability." (PMID 40470379, 2025). "The protective effect of 3,4‐cPP on CLP‐induced sepsis was abolished in either EC–Sirt1 or MФ–Sirt1 cKO." (PMID 40470379, 2025). "Further research is warranted to dissect the mechanism underlying these beneficial effects and to explore the clinical applicability of Sirt1 activators in treating severe infections and preventing sepsis-related complications." (PMID 41096578, 2025). "Interferon β induces SIRT1 expression in macrophages, alleviating sepsis by inhibiting proinflammatory cytokines." (PMID 40470379, 2025). "Here, we demonstrate that 3,4‐cPP, a SIRT1 inducer, effectively protects against sepsis by reducing vascular leakage and regulating inflammatory responses." (PMID 40470379, 2025). "Mitotherapy mitigated sepsis-induced brain injury by improving mitochondrial function, biogenesis, and dynamics within the SIRT-1/PGC-1α network and concurrently suppressing inflammation." (PMID 40584438, 2025). "The overexpression of growth differentiation factor 11 (GDF11) further inhibits ferroptosis by promoting the activity of SIRT1, providing a new molecular target and therapeutic strategy for treating sepsis related ALI." (PMID 40109363, 2025). "This suggests that 3,4‐cPP also affects sepsis‐induced endothelial damage by inducing SIRT1 expression." (PMID 40470379, 2025). "We previously identified SIRT1 as a key target for sepsis treatment, capable of controlling inflammation and strengthening the blood vessel wall." (PMID 40470379, 2025).
Sepsis (continued). "This elevation exacerbates sepsis-induced renal injury by targeting SIRT1, inhibiting the NF-κB pathway, and promoting M1 macrophage polarization." (PMID 40332144, 2025). "In sepsis, SIRT1 limits inflammation in myeloid cells, reducing organ failure and improving survival rates." (PMID 41416347, 2025). "SIRT1 plays a protective role in organ damage such as sepsis-induced acute kidney injury by activating autophagy, further supporting its importance as a key regulatory node." (PMID 41252417, 2025). "This improvement aligns with increased expression of genes regulating mitochondrial biogenesis (SIRT-1 and PGC-1α), the promotion of the Mfn2 gene associated with mitochondrial fusion, and suppressing inflammatory response following CLP-induced sepsis." (PMID 40584438, 2025). "Anthraquinones derived from Rhei Radix et Rhizoma, such as emodin and rhein, protect against lung and kidney injury in experimental sepsis models through SIRT1/HMGB1 and NF-κB pathways, respectively." (PMID 41357500, 2025). "In sepsis-associated AKI, GAS5 limits tubular pyroptosis by regulating miR-579-3p and activating the SIRT1–PGC-1α–Nrf2 pathway." (PMID 41303683, 2025). "In ALI induced by sepsis, SIRT1 plays a role in inhibiting ferroptosis by activating the NADPH oxidase 4 signaling pathway, which reduces the production of ROS and the level of lipid peroxidation, and maintains the balance of iron metabolism in cells." (PMID 40109363, 2025). "In sepsis associated acute kidney injury (SA-AKI), the exercise hormone irisin mitigates ferroptosis and kidney damage through the SIRT1/Nrf2 signaling pathway." (PMID 40109363, 2025). "In a similar manner, microRNA-133a-3p has been shown to offer protection against sepsis-induced acute respiratory distress syndrome (ARDS) by modulating SIRT1, a pivotal regulator of inflammation and oxidative stress." (PMID 40135054, 2025). "First, our study focused on the acute phase of pneumonia and sepsis; the long-term effects of Sirt1 activation on immune function and pathogen clearance were not explored." (PMID 41096578, 2025). "A self-assembling nanopeptide and resveratrol hydrogel composite enhances Sirt1-mediated deacetylation of p62, promoting mitochondrial autophagy and immunometabolic remodeling, thereby mitigating sepsis-induced inflammation." (PMID 41306613, 2025). "SIRT1 attenuates sepsis-induced acute kidney injury via Beclin1 deacetylation-mediated autophagy activation." (PMID 40989844, 2025). "In vivo analyses reveal a physical interaction between SIRT1 and HMGB1 within the nucleus, with SIRT1 modulating the acetylation of HMGB1 to combat sepsis-induced liver damage." (PMID 38690282, 2024). "In a mouse model of sepsis, through deacetylation of NF-κB, SIRT1 renders it inactive, thereby diminishing pro-inflammatory response levels." (PMID 39234245, 2024). "Hydrogen-rich saline has been shown to elicit anti-inflammatory effects by upregulating the SIRT1/NF-κB signaling pathway to prevent microvascular endothelial glycocalyx shedding and maintain micro-endothelial function in sepsis-induced kidney injury." (PMID 39598406, 2024). "The upregulation of miR‐195 leads to the exacerbation of sepsis by its own targeting of SIRT1, thus promoting apoptosis of intestinal epithelial cells." (PMID 38014923, 2024). "The long non-coding RNA OIP5-AS1 exhibits a trend of expression that parallels SIRT1 during sepsis-induced lung injury." (PMID 38690282, 2024). "Recent studies have expanded the spotlight from SIRT1 to include SIRT3 as a crucial participant in the protective effects of melatonin against sepsis-induced MODS." (PMID 38690282, 2024).